IGHV4OR15-8 (immunoglobulin heavy variable 4/OR15-8 (non-functional))
Synonyms: IGHV4/OR15-8; IGHV4OR158; formerly VSIG6
Gene: Immunoglobulin variable (V) gene on chromosome 15 (22,184,967 to 22,185,402, reverse strand). Ensembl gene ENSG00000259261.
Gene Ontology:
Molecular function: antigen binding
Biological process: immunoglobulin mediated immune response
Cellular component: extracellular region; plasma membrane
Homologues: Paralogues in human: IGHV4-4 (97% identical), IGHV4-59 (91% identical), IGHV4-61 (91% identical), IGHV4-39 (90% identical), IGHV4-28 (89% identical), IGHV4-31 (89% identical), IGHV4-34 (86% identical), IGHV6-1 (61% identical), IGHV2-26 (54% identical), IGHV2-5 (52% identical), IGHV3-11 (52% identical), IGHV2-70 (51% identical), and 65 more.